RNU6-1279P (RNA, U6 small nuclear 1279, pseudogene)
Gene: Small nuclear RNA gene on chromosome 3 (196,393,710 to 196,393,812, reverse strand). Ensembl gene ENSG00000206644.
Homologues: Orthologues: chimpanzee U6 (99% identical), rabbit U6 (89% identical), mouse Gm24261 (88% identical), rat U6 (87% identical), rabbit U6 (84% identical), pig U6 (83% identical), rabbit U6 (82% identical), rabbit U6 (76% identical). Paralogues in human: RNU6-12P (90% identical), RNU6-13P (90% identical), RNU6-25P (90% identical), RNU6-32P (90% identical), RNU6-41P (90% identical), RNU6-1 (89% identical), RNU6-17P (89% identical), RNU6-18P (89% identical), RNU6-2 (89% identical), RNU6-36P (89% identical), RNU6-3P (89% identical), RNU6-49P (89% identical), and 1288 more.